CRLF1 (cytokine receptor like factor 1)
Description:
Functions as secretory protein carrier chaperone that promotes cellular release. Also functions as a cytokine subunit within the CRLF1-CLCF1 heterodimer, which engages the CNTF receptor complex (CNTFR, IL6ST/gp130, LIFR). As part of the CRLF-CLCF1 complex, binds to CNTFR, induces dimerization of the IL6ST/gp130 and LIFR, which activates JAK tyrosine kinases (JAK1 or JAK2 and to lesser extent TYK2) bound to their intracellular domains. These kinases subsequently phosphorylate IL6ST/gp130 and LIFR. The tyrosine phosphorylated signaling receptors serve in turn as docking sites for recruitment and activation of signal transducer and activators of transcription (STAT3 and to lesser extent STAT1). Moreover, CLCF1/CLF heterodimer induces tyrosine phosphorylation of PTPN11, that associates with IL6ST/gp130-LIFR, which in turn recruits PIK3 protein kinase followed by AKT protein phosphorylation. Participates in the survival of embryonic motor neurons. May also play a regulatory role in the immune system.
Synonyms: CLF-1; CLF; CISS; CISS1; NR6; zcytor5
Tractability: Antibody: UniProt places it where antibodies can reach, with high confidence; its Gene Ontology location is reachable by antibodies, with high confidence; UniProt predicts a signal peptide or a membrane-spanning region.
Gene: Protein-coding gene on chromosome 19 (18,572,220 to 18,607,741, reverse strand). Ensembl gene ENSG00000006016.
Subcellular location: Secreted
Pathways (Reactome):
Immune System: IL-6-type cytokine receptor ligand interactions; Interleukin-27 signaling
Gene Ontology:
Molecular function: ciliary neurotrophic factor receptor binding; cytokine activity; cytokine binding; protein binding; protein carrier chaperone; cytokine receptor activity
Biological process: cell surface receptor signaling pathway via STAT; cytokine-mediated signaling pathway; negative regulation of neuron apoptotic process; positive regulation of cell population proliferation; protein secretion; negative regulation of motor neuron apoptotic process; ureteric bud development
Cellular component: CRLF-CLCF1 complex; extracellular region; cytosol; external side of plasma membrane; receptor complex
Genetic constraint (gnomAD): Loss-of-function variants: 34 observed, 43.3 expected, observed/expected ratio (o/e) 0.79, 90% interval 0.6 to 1.04. The upper end of that interval is the gene's LOEUF score, 1.04, which puts it in group 4 of 6, group 1 being the genes least tolerant of losing a copy. Missense variants: 504 observed, 537.37 expected, observed/expected ratio (o/e) 0.94, 90% interval 0.87 to 1.01. Synonymous variants: 235 observed, 228.32 expected, observed/expected ratio (o/e) 1.03, 90% interval 0.93 to 1.15.
Homologues: Orthologues: macaque CRLF1 (99% identical), dog CRLF1 (98% identical), chimpanzee CRLF1 (97% identical), mouse Crlf1 (95% identical), pig CRLF1 (95% identical), rat Crlf1 (95% identical), guinea pig CRLF1 (94% identical), tropical clawed frog crlf1 (69% identical). Paralogues in human: LEPR (21% identical), IL6ST (20% identical), CSF3R (20% identical), IL31RA (19% identical), IL12RB2 (18% identical), LIFR (18% identical), PRLR (18% identical), IL23R (17% identical), OSMR (17% identical), CSF2RA (16% identical), IL27RA (13% identical), CNTFR (13% identical), and 11 more.
Diseases named in the same sentence as CRLF1 in open-access papers:
CRLF1 is named in the same sentence as 42 diseases in open-access papers, as found by Europe PMC text mining. Sharing a sentence is not in itself a finding about the gene and the disease. The quoted sentences say what the papers report.
cold-induced sweating syndrome (7 papers, 2006 to 2025). Cold-induced sweating syndrome (CISS) is characterized by profuse sweating (involving the chest, face, arms and trunk) induced by cold ambient temperature. "Mutations in CRLF1 or CLCF1 are associated with Crisponi/cold-induced sweating syndrome (CS/CISS)." (PMID 35055176, 2022). "Genetic mutations in cytokine receptor-like factor 1 (CRLF1), that plays a role in this process, cause the Cold Induced Sweating Syndrome (CISS)." (PMID 33333929, 2020). "Crisponi syndrome is now considered to be the same disorder as cold-induced sweating syndrome, and cold-induced sweating syndrome is caused by mutations in the CLCF-1 or CRLF-1 genes." (PMID 24618404, 2014). "Mutation in the cytokine receptor-like factor 1 and the cardiotrophin-like cytokine (CRLF1 or CLCF1 genes) phenotypically presents as cold induced sweating syndrome (CISS), which is a rare autosomal recessive disorder." (PMID 24073352, 2013).
Crisponi syndrome (5 papers, 2013 to 2026). "Whole exome sequencing confirmed a homozygous likely pathogenic variant in the CRLF1 gene, consistent with Crisponi syndrome." (PMID 42281720, 2026). "Due to suspect of Crisponi syndrome, Sanger sequencing detected two heterozygous CRLF1 variants—c.226T>G (p.W76G) in exon 2 and C.676-677insA (p.T226NfsX104) in exon 4, interpreted as pathogenic." (PMID 41227153, 2025). "Similar to Crisponi syndrome, which involves variants in CRLF1 or CLCF1 genes, SWS shares overlapping clinical features but has distinct genetic origins." (PMID 41211063, 2025). "Regarding the genetic basis of this disease, the CRLF1 variants identified in our patients were already reported in the original description of Crisponi syndrome." (PMID 41227153, 2025). "Crisponi syndrome, also referred to as cold-induced sweating syndrome type 1, is an uncommon autosomal recessive disorder caused by mutations in the cytokine receptor-like factor 1 (CRLF1) gene." (PMID 42281720, 2026). "In addition to cold sweat syndrome and Crisponi syndrome, mutations in the CRLF1 gene can also cause facial muscle atrophy, scoliosis and craniofacial deformity." (PMID 33072735, 2020). "While mutations in CRLF1 is associated with cold sweat syndrome and Crisponi syndrome, the craniofacial malformations of these patients suggest that CRLF1 may be important for the formation of the ECM." (PMID 33072735, 2020).
papillary thyroid carcinoma (5 papers, 2018 to 2024). "in addition, CRLF1 is considered as a potential target gene of a tumor suppressor TNRC6C in papillary thyroid cancer." (PMID 34656128, 2021). "In our previous study, we have shown that CRLF1 can promote proliferation and metastasis of papillary thyroid carcinoma (PTC); however, the mechanism is unclear." (PMID 32982961, 2020). "CRLF1 interacts with MYH9 to promote cell proliferation and metastasis via the ERK/ETV4 axis in papillary thyroid carcinoma." (PMID 37875476, 2023). "For example, the expression level of CRLF1 is increased in lung adenocarcinoma tissues compared to normal tissues and promotes malignant phenotypes of papillary thyroid carcinoma by activating the MAPK/ERK and PI3K/AKT pathways." (PMID 34656128, 2021).
osteoarthritis (4 papers, 2021 to 2024). A noninflammatory degenerative joint disease occurring chiefly in older persons, characterized by degeneration of the articular cartilage, hypertrophy of bone at the margins and changes in the synovial membrane. "Previous studies have shown that CRLF1 is highly upregulated in osteoarthritic and damaged cartilage, suggesting a role for CRLF1 in osteoarthritis." (PMID 38727293, 2024). "Suppression of CRLF1 via activation of miR-320 promotes the chondrogenic differentiation of BMSCs and protects cartilage tissue from damage in osteoarthritis." (PMID 35055176, 2022). "Suppression of CRLF1 promotes the chondrogenic differentiation of BMSCs and protects cartilage tissue from damage in osteoarthritis via activation of miR-320." (PMID 34551709, 2021). "CRLF1 is reportedly highly expressed in damaged human knee osteoarthritic cartilage and involved in osteoarthritis downstream of TGF-beta." (PMID 34551709, 2021). "This evidence suggests that the CRLF1/CLCF1 complex may disrupt cartilage homeostasis and promote the progress of osteoarthritis." (PMID 35055176, 2022).
colorectal cancer (3 papers, 2021 to 2022). A primary or metastatic malignant neoplasm that affects the colon or rectum. "Taken together, these results suggested that CRLF1 mediates the stemness-promoting effect of miR-3065-3p in colorectal cancer cells." (PMID 34656128, 2021). "Our data suggest that miR-3065-3p promoted the stemness and metastasis of colorectal cancer by targeting CRLF1." (PMID 34656128, 2021). "It was also confirmed that the mRNA and protein expression of CRLF1 was markedly downregulated in colorectal cancer tissues compared to corresponding adjacent normal tissues." (PMID 34656128, 2021). "Collectively, these results demonstrated that CRLF1 inhibits the tumorigenesis and metastasis of colorectal cancer in vivo." (PMID 34656128, 2021). "To investigate the impact of CRLF1 on the tumorigenesis and metastasis of colorectal cancer, we established a xenograft tumor model and liver metastasis model of colorectal cancer using HCT116-overexpressing CRLF1 or control cells." (PMID 34656128, 2021). "Collectively, these results reveal that CRLF1 is a direct target of miR-3065-3p and that its expression is downregulated by miR-3065-3p in colorectal cancer." (PMID 34656128, 2021). "CRLF1, as the target for miR-3065-3p, could promote the stemness and metastasis of colorectal cancer." (PMID 35748788, 2022). "Furthermore, we demonstrated that miR-3065-3p promoted the stemness and metastasis of colorectal cancer by targeting Cytokine Receptor Like Factor 1 (CRLF1) in vitro and in vivo." (PMID 34656128, 2021). "Moreover, CRLF1 mediated the promoting effect of miR-3065-3p on stemness-related transcription factor expression in colorectal cancer cells." (PMID 34656128, 2021). "In addition, CRLF1 expression was negatively correlated with miR-3065-3p in colorectal cancer tissues." (PMID 34656128, 2021). "Moreover, the correlation between CRLF1 expression and miR-3065-3p was analyzed in colorectal cancer tissues." (PMID 34656128, 2021). "Moreover, analysis of the TCGA database showed that CRLF1 expression was reduced in colorectal cancer patients compared to normal subjects." (PMID 34656128, 2021). "And, CRLF1 mediated the effects of miR-3065-3p on promoting stemness of colorectal cancer cells." (PMID 34656128, 2021). "Furthermore, CRLF1 was the downstream target of miR-3065-3p and inhibited the stemness of colorectal cancer." (PMID 34656128, 2021). "Finally, the effect of CRLF1 on the stemness and metastasis of colorectal cancer in vitro and in vivo was assessed." (PMID 34656128, 2021). "Furthermore, we found that CRLF1 was the direct target of miR-3065-3p and functioned as a suppressor of the stemness of colorectal cancer cells." (PMID 34656128, 2021). "Then, the effect of CRLF1 on the stem cell-like characteristics of colorectal cancer was evaluated." (PMID 34656128, 2021). "To determine the role of CRLF1 in colorectal cancer, we established a HCT116 colorectal cancer cell line stably overexpressing CRLF1." (PMID 34656128, 2021).
breast carcinoma (2 papers, 2016 to 2024). "We found five proteins associated with the risk of breast cancer, such as STC2 and CRLF1 [1.33 (1.23–1.44) and 1.31 (1.21–1.42)]." (PMID 38750076, 2024). "Furthermore, there have been no reports on the activity of CLIP4, CAPN2, CRLF1, CYBRD1, PHF10, and TRHDE in breast cancer or chemoresistance, thus making them new candidates for understanding breast cancer, the EMT, and chemoresistance." (PMID 27094684, 2016).
ovarian carcinoma (2 papers, 2024 to 2025). A malignant neoplasm originating from the surface ovarian epithelium. "This ultimately restores ovarian cancer cell susceptibility to cisplatin-induced pyroptosis, shed light on the crucial role of CRLF1’s adaptor function in regulating AKT activation and chemoresistance." (PMID 39256356, 2024). "In conclusion, overexpression of binding-defective CRLF1 variants sensitizes ovarian cancer cells to DDP-induced pyroptosis by competitively inhibiting the AKT-SIN1 interaction and reducing AKT phosphorylation." (PMID 39256356, 2024). "The results showed that high expression levels of CRLF1 were significantly associated with shorter PFS, suggesting a potential role of CRLF1 in conferring chemoresistance to ovarian cancer." (PMID 39256356, 2024). "The binding-defective CRLF1 variants could be potential tumor-specific polypeptide drugs to enhance chemotherapy effectiveness as adjuvant therapy in ovarian cancer." (PMID 39256356, 2024). "Moreover, higher CRLF1 expression was associated with poorer survival outcomes in ovarian cancer patients." (PMID 39256356, 2024). "Binding-defective CRLF1 variants could be developed as tumor-specific polypeptide drugs to enhance chemotherapy for ovarian cancer." (PMID 39256356, 2024). "In summary, CRLF1 enhances chemoresistance by inhibiting pyroptosis and increasing AKT inhibitor susceptibility in ovarian cancer." (PMID 39256356, 2024). "CRISPR-Cas9 screening suggested that CRLF1 more likely directly inhibits cell death to enhance chemoresistance in ovarian cancer." (PMID 39256356, 2024). "To understand how CRLF1 confers chemoresistance in ovarian cancer cells, we investigated its involvement in the GP130 signaling pathway." (PMID 39256356, 2024). "Our investigation unveils CRLF1, a secreted protein, as a novel regulator influencing pyroptosis and cisplatin resistance in ovarian cancer independent on its secretion." (PMID 39256356, 2024). "Analysis of TCGA database and immunohistochemical staining results revealed that both mRNA and protein expression levels of CRLF1 were upregulated in ovarian cancer, with further increases observed following DDP treatment." (PMID 39256356, 2024). "Overall, this work elucidates a novel CRLF1-SIN1/AKT-pyroptosis axis that drives chemoresistance in ovarian cancer, firmly establishing CRLF1 as a promising therapeutic target warranting further exploration." (PMID 39256356, 2024). "In brief, CRLF1 functions as an oncogene driving the ovarian cancer cell proliferation and invasion." (PMID 39256356, 2024). "Our research shows high CRLF1 expression in ovarian cancer correlates with poor patient survival and chemoresistance." (PMID 39256356, 2024). "Collectively, these data indicate that high CRLF1 levels confer resistance to DDP in ovarian cancer cells." (PMID 39256356, 2024). "However, its involvement in programmed cell death regulation and the precise mechanisms orchestrating CRLF1’s activation of the PI3K/AKT pathways in ovarian cancer remain obscure." (PMID 39256356, 2024). "Notably, silencing CRLF1 curtailed proliferation, migration, and invasion in ovarian cancer cell lines, including A2780, CaoV3, and SKOV3." (PMID 39256356, 2024). "Thus, CRLF1 critically regulates chemoresistance in ovarian cancer by modulating AKT/SIN1-dependent pyroptosis." (PMID 39256356, 2024). "This prompted us to initially investigate the functions of CRLF1 in ovarian cancer progression." (PMID 39256356, 2024). "Consequently, CRLF1 stifles pyroptosis by augmenting mTORC2-mediated AKT activation, providing ovarian cancer cells with a survival advantage against cisplatin cytotoxicity." (PMID 39256356, 2024). "RNA sequencing of ovarian carcinoma-TA-MSCs identifies a distinct predictive algorithm comprising six genes: Annexin A8-like protein 2 (ANXA8L2), Collagen Type XV Alpha 1 Chain (COL15A1), Cytokine Receptor Like Factor 1 (CRLF1), GATA Binding Protein 4 (GATA4), Iroquois Homeobox 2 (IRX2), and TGF‐β2." (PMID 40676710, 2025).
Achalasia (1 paper, 2022). A disorder of esophageal motility characterized by the inability of the lower esophageal sphincter to relax during swallowing and by inadequate or lacking peristalsis in the lower half of the body of the esophagus. "Interestingly, in this respect, mutations in CRLF1 have also been found in patients with familial achalasia, suggesting a role of CRLF1 signalling in the relaxation of the lower oesophageal sphincter." (PMID 35055176, 2022).
anaplastic thyroid carcinoma (1 paper, 2018). "Compared with those in a normal epithelial cell line (Nthy-ori-3-1), CRLF1 mRNA and protein levels were increased in a PTC cell line (B-CPAP) and an anaplastic thyroid carcinoma (ATC) cell line (8305C)." (PMID 29515111, 2018).
colon cancer (1 paper, 2021). "The loss-of-function assay indicated that CRLF1 might play functional roles in the sophisticated regulation of colon cancer progression, suggesting that it could be a potential therapeutic target for CRC." (PMID 34211976, 2021).
glioma (1 paper, 2023). A benign or malignant brain and spinal cord tumor that arises from glial cells (astrocytes, oligodendrocytes, ependymal cells). "PLOD2, Spp1, SPOCK1 and CRLF1 can also serve as new targets for anti-tumor microenvironment therapy of glioma." (PMID 36819132, 2023).
Hypernatremia (1 paper, 2022). An abnormally increased sodium concentration in the blood. "In one recent CS/CISS1 report, the patient presented with urinary system complications, including a small ectopic nonfunctioning right kidney and persistent mild hypernatremia, suggesting a possible role of CRLF1 in renal development." (PMID 35055176, 2022).
Hypertension (1 paper, 2021). The presence of chronic increased pressure in the systemic arterial system. "Certain genes involved in the pathogenesis of hypertension—Alb, Chrm2, Xirp1, Kcnq1, Slc5a7, Kcnh1, Ache, Crlf1 and Galr2— should also be studied." (PMID 34603037, 2021).
idiopathic pulmonary fibrosis (1 paper, 2022). Idiopathic pulmonary fibrosis (IPF) is a nonneoplastic pulmonary disease that is characterized by the formation of scar tissue within the lungs in the absence of any known cause. "CRLF1 was among the most highly up-regulated gene in idiopathic pulmonary fibrosis (IPF), a progressive and typically fatal lung disease, compared with normal controls." (PMID 35055176, 2022).
lymph node metastasis (1 paper, 2018). "Taken together, these results indicate that CRLF1 is highly expressed in PTC, particularly in patients with lymph node metastasis or in the late stages of the disease." (PMID 29515111, 2018). "CRLF1 expression levels were higher in patients with lymph node metastasis (N1) than those in patients without lymph node metastasis (N0, P < 0.01)." (PMID 29515111, 2018).
myocardial infarction (1 paper, 2020). Gross necrosis of the myocardium, as a result of interruption of the blood supply to the area, as in coronary thrombosis. "Fibroblasts from GA patient 2 (sub-cluster 7), meanwhile, expressed elevated amounts of SPOCK1 (Avg-Log FC: 0.99), CRLF1 (Avg-Log FC: 1.38), and COMP (Avg-Log FC: 1.35), a cartilage protein that is upregulated in matrix-producing fibroblasts after myocardial infarction." (PMID 33053333, 2020).
neuroblastoma (1 paper, 2013). Neuroblastoma (NB) is the most common solid, extracranial childhood tumor. "Because inhibition of signaling by the CLC/CLF receptor has previously been connected to oxidative stress, we chose to focus on CRLF1 as a potential mediator of oxidative stress resistance during differentiation of neuroblastoma cells." (PMID 23818941, 2013).
osteoporosis (1 paper, 2021). A condition of reduced bone mass, with decreased cortical thickness and a decrease in the number and size of the trabeculae of cancellous bone (but normal chemical composition), resulting in increased fracture incidence. "Crlf1 is a member of the ciliary neurotrophic factor receptor pathway, and is involved in the anabolic therapy of osteoporosis through regulating osteoblast proliferation and bone formation." (PMID 33568122, 2021).
polyarticular JIA (1 paper, 2022). "CRLF1, MFAP5, and TNXB are overexpressed in persistent oligoarticular JIA FLS compared to polyarticular JIA FLS." (PMID 36167601, 2022).
pulmonary fibrosis (1 paper, 2022). Chronic progressive interstitial lung disorder characterized by the replacement of the lung tissue by connective tissue, leading to progressive dyspnea, respiratory failure, or right heart failure. "In addition, CRLF1/CLCF1 reduced pulmonary fibrosis, and further investigation is needed to determine whether CRLF1 has therapeutic potential as an antifibrotic agent." (PMID 35055176, 2022).